FOXO1 (forkhead box O1)
Diseases named in the same sentence as FOXO1 in open-access papers (continued):
Sharing a sentence is not in itself a finding about the gene and the disease.
tumor (continued). "To further understand the effect of FOXO1 overexpression on CAR T cell phenotype, we performed scRNA-seq analyses on CAR T cells prior to and after co-culture with MCF7 tumour cells." (PMID 38600376, 2024). "In both cases, FOXO1 expression in the patient-derived CAR T cells significantly enhanced the numbers of CAR T cells in both the spleens and tumours of treated mice." (PMID 38600376, 2024). "Within the study, clinical risk stratification is based on clinical features at first presentation including age, disease site, post-surgical clinical (IRS) group, tumour size, nodal status, and PAX: FOXO1 fusion status." (PMID 38473359, 2024). "Forkhead box protein O1 (FOXO1) belongs to the forkhead box O (FOXO) family of transcription factors, which is a tumor-suppressing factor that inhibits carcinogenesis." (PMID 38617001, 2024). "The present study correlates the expression levels of critical genes (PIK3CA, PTEN, AKT1, FOXO1, and FRAP) in 60 tumor tissues with clinicopathological and demographic characteristics." (PMID 38891994, 2024). "In conclusion, our study provides the first preliminary evidence that HOXB2 acts as a tumor promoter in NPC progression and enhances radioresistance by regulating FOXO1 expression." (PMID 38617001, 2024). "Compared with normal tissues, six proteins (GALNT6A, FOXO1, ACSM3, DNAJA1, PRDX5, and SERPINB9) were notably overexpressed in tumour tissues." (PMID 39030559, 2024). "FOXO‐1, FOXO‐3, and FOXO‐4 are partially redundant tumor suppressors that induce pro‐apoptotic genes such as TRAIL and cell cycle inhibitors such as cyclin‐dependent kinase inhibitor 1B (CDKN1B; encoding p27) in some settings." (PMID 37584250, 2023). "Despite these limitations, our study forms an important addition to prognostic impact of FOXO1 fusions in RMS; more so in a substantive cohort with larger tumours and higher incidence of nodal spread." (PMID 37138963, 2023). "Recent research demonstrated that miR-183-5p can increase HCC cell proliferation by suppressing the expression of tumor suppressors (including AKAP12, DYRK2, FOXN3, FOXO1 and LATS2) which is agreement with our results." (PMID 37168369, 2023). "FOXO1 and FOXO3 have been found to be highly phosphorylated and inactivated, suggesting tumour suppressive functions for FOXOs in MM." (PMID 37275916, 2023). "The PI3K/AKT inhibition by Idelalisib unexpectedly induces GSK3/FOXO1 activation, leading to the upregulation of IGF1R, which in turn activates the MAPK signaling in the Idelalisib-treated tumor cells." (PMID 36831678, 2023). "The PAX3::FOXO1 fusion protein is a key regulator of FP-RMS oncogenesis and its unique expression in tumor tissues supports development of direct inhibitors." (PMID 37732905, 2023). "The "O" subfamily of forkhead box transcription factors consists of four members, including FOXO1 (FKHR), FOXO3 (FKHRL1), FOXO4 (AFX), and FOXO6, generally considered tumor suppressors via inducing apoptosis and inhibiting proliferation." (PMID 37821870, 2023). "While FOXO1-fusions have superior prognostic utility compared to histology alone in localised, favourable-site RMS, traditional prognostic factors (tumour size and nodal metastases) impacted outcome the most in this subset." (PMID 37138963, 2023). "Similar to FOXO1, FOXO3 (also known as FOXO3a) is generally considered a tumor suppressor in different cancers, and its sub-cellular localization was shown to be crucial for its activity." (PMID 37821870, 2023). "CircRPN2 is also an endogenous competitor for miR-183-5p binding, which upregulates forkhead box protein O1 (FOXO1) expression to suppress glucose metabolism and tumor progression." (PMID 37394582, 2023). "HDAC inhibitors have been shown to upregulate expression of the FOXO1 tumor suppressor and they also work synergistically with PI3K/mTOR inhibitors to reduce tumor growth." (PMID 37568705, 2023).
tumor (continued). "We evaluated the panel using tumor DNA samples from five patients (four with EWSR1 fusions and one with a FOXO1 fusion, as previously identified by OncoKids®34)." (PMID 36805676, 2023). "Forkhead box protein O1 (FOXO1), a member of forkhead box O (FOXO) family of transcription factors, regulates a wide range of molecular signals in tumor, liver, and brain and plays a vital role in cell apoptosis, inflammation, and tissue development." (PMID 35198097, 2022). "Forkhead box O1 (FoxO1) silencing enhances NPC progression, whereas STAT3 silencing prevents tumor progression." (PMID 36313702, 2022). "Genetic or pharmacological inhibition of FOXO1 collapses the MCL transcriptional network and induces tumor cell death in vitro and in vivo." (PMID 36282572, 2022). "The bioinformatics analysis of miR-21 predicted targets suggested that multiple tumor suppressor genes, including programmed cell death 4 (PDCD4), tropomyosin (TPM1), PTEN, and Fork-head box O1 (FoxO1) related to apoptosis pathways, have miR-21 binding sites." (PMID 36180486, 2022). "In the tumor tissues of AGK knockdown group, we found that the expression of BCL-2 was upregulated, but the phosphorylation of FOXO1 and AKT was significantly decreased." (PMID 35910796, 2022). "Most importantly, we demonstrated the existence of miR-9-5p/FOXO1/CPEB3 FFL and validated its regulation role in HCC tumor proliferation in vivo and in vitro." (PMID 35805200, 2022). "In fact, the tumor suppressor role of MBNL1-AS1 is exerted through decreasing miR-135a levels and influencing activity of PHLPP2/FOXO1 axis." (PMID 36147505, 2022). "FOXO1 and FOXO3a protein expression was significantly increased in cells treated with OSU-ERb-12, a potential mechanism for its tumor-suppressive effects." (PMID 35574319, 2022). "In conclusion, changes in tumor metabolism, particularly in mitochondria respiration, resulted in considerable changes in tumor characteristics through the PI3K/Akt/FoxO1/Cyclin D1 pathway." (PMID 35865479, 2022). "For example, hub node gene CPEB3 has been described as a newly discovered tumor suppressor in HCC, and hub TF FOXO1 was responsible for blocking HCC proliferation." (PMID 35805200, 2022). "More importantly, we further demonstrated that TRIB3 interacted with AKT1 to up-regulate FOXO1 and SOX2 expression, which was indispensable for the pro-tumor effects induced by integrin αvβ3." (PMID 35473511, 2022). "At the same time, the results of immunohistochemical staining and Western blotting suggested a decline in the HDAC3 expression in the tumor tissues of CDM-treated mice, while FOXO1 acetylation level was increased in a dose-dependent manner." (PMID 35126526, 2022). "This immune response reduced the levels of CD3d, IL-2, IL-2 receptor chain alpha, forkhead box O1 (FOXO1), and nuclear factor of activated T cells 5 (NFAT5); a microenvironment that supports tumor progression." (PMID 36226048, 2022). "Here, we investigated the synergistic effect of combination treatment with both of these drugs in inducing FoxO1 and repressing Twist1 expression and thereby inhibiting EMT and tumor regression." (PMID 33772986, 2022). "To further test the role of the CDK1-dependent cell cycle pathway, we analyzed the role of Forkhead Box O1 (FOXO1), which has been shown to have a direct link downstream of CDK1 and is involved in cell death, repair of DNA damage and tumor suppression." (PMID 35132135, 2022). "Gain- and loss-of-function analyses indicated that high expression of miR-9-5p was associated with aggressive tumor phenotypes and poor clinical diagnosis, while FOXO1 and CPEB3 inhibited tumor proliferation." (PMID 35805200, 2022).
tumor (continued). "The very well controlled intrinsic modes of NK cell development, differentiation, and maturation by FOXO1 and FOXO3 revealed in our study can drive future efforts to develop anti-tumor and anti-viral immunotherapies targeting FOXO proteins." (PMID 35757763, 2022). "In human DLBCL tumor tissues, the expression of AGK inversely correlated with BCL-2 expression, as well as the amounts of nuclear FOXO1." (PMID 35910796, 2022). "PI3K inhibitors are also effective in inducing the expression of FOXO1 and act synergically with HDAC modulators, inhibiting tumor proliferation and prolonging survival in group 3 MB–bearing mice." (PMID 35053495, 2022). "Past efforts have demonstrated that miR-9-5p and FOXO1 were involved in the progression of HCC in vivo and CPEB3 silencing increased tumor size and weight in HCC." (PMID 35805200, 2022). "For the patients with ARMS (P18 and P25), we detected a PAX3-FOXO1 fusion, whereas FOXO1 break-apart FISH demonstrated 0% positive tumor cells, and patients were diagnosed based on clinicopathological and morphological findings only." (PMID 36232302, 2022). "The FOXO1-mediated inhibition of PDAC formation is partially due to the inhibition of β-catenin activity, which promotes tumour formation." (PMID 35324773, 2022). "miR-21 acts as an oncogene by directly targeting the tumor suppressors PTEN, PDCD4 and FOXO1, which leads to the activation of PI3K/AKT/mTOR oncogenic pathway." (PMID 34679437, 2021). "MiRNAs (miR-130a, miR-135b, miR-155) wrapped in tumor-derived exosomes have been found to promote GC angiogenesis and metastasis through c-MYB, forkhead box O1 (FOXO1), and FOXO3 respectively." (PMID 34268118, 2021). "Over-expression of forkhead box protein O1 (FOXO1), a down-regulated tumor suppressor in EC, has been observed to inhibit proliferation of Ishikawa cells as well as suppression of cell migration and invasion." (PMID 33602218, 2021). "FOXO1 is a key downstream effector of PTEN and a tumor suppressor in PCA, which has been reported extensively." (PMID 34552661, 2021). "Tumor tissue detection results showed that FoxO1 and SREBP-1c inhibited each other, and the net effect of FoxO1 and SREBP-1c facilitated the progression of HB by regulating fatty acid metabolism in vivo." (PMID 34539243, 2021). "Therefore, we conclude that circMRPS35 combined with KAT7 acetylation may mediate FOXO1 and FOXO3a to interfere with tumor metastasis, laying a solid foundation for tumor intervention, which may be a major breakthrough in regulating tumors at the level of histone acetylation." (PMID 34796685, 2021). "MEG3 inhibits cell proliferation and metastasis by regulating the expression of miR-5195-3p and FOXO1 in HCC cells, and inhibits tumor growth in vivo." (PMID 34895065, 2021). "Contrary to its paralog FOXO1, the implication of FOXO3, a well-established tumor suppressor with regular overlap and functional redundancy, has not received particular attention in PAH." (PMID 33805714, 2021). "Collectively, our data revealed a tumor suppressor role of RNF152 and a connection between RNF152 and FoxO1 in HCC." (PMID 33602225, 2021). "On the one hand, the widely studied FOXO1 regulates cellular function as a tumor inhibitor; on the other hand, FOXO3 and FOXO6 play important roles in promoting tumor growth and invasion and maintaining tumor survival." (PMID 34123834, 2021). "In the current experiments, we set about to examine the regulatory effects that IGF2BP2 on GBM cell chemoresistance and analyze the potential regulatory network of the IGF2BP2/DANCR/FOXO1/PID1, aiming to provide a novel antitumor target for tumor treatment." (PMID 35141227, 2021). "We knocked down FoxO1 and SREBP-1c simultaneously in Huh-6 cells and found that fatty acid metabolism of Huh-6 cells was inhibited, and cell function and tumor-forming ability were weakened." (PMID 34539243, 2021).
tumor (continued). "In summary, we have revealed a tumor suppressor role of RNF152 and a connection between RNF152 and FoxO1 in HCC." (PMID 33602225, 2021). "Our previous research found that FoxO1 acts as a regulator of anti-tumor effect in TAMs, and we found a connection between hypoxia, FoxO1, MHC-II, and tumor growth." (PMID 32973162, 2020). "miR-21 activates the EGFR/AKT signaling pathway via targeting tumor suppressor genes such as PTEN, PDCD4, APAF1, TPM1, TIMP3, RECK, FOXO1 and SPRY240." (PMID 32019988, 2020). "In previous studies, we also observed that miR-133a-3p, miR-5188, miR-3188, miR-374a, and miR-296-3p, respectively were modulated by VPS33B, HBx, FOXO1, PDCD4, and HDGF involving in the tumor pathogenesis induced by these genes." (PMID 32641685, 2020). "We observed that, compared to WT tumor animals, CCR2KO tumor animals had decreased induction of Murf1 and Foxo1, confirming that there was decreased catabolic drive in CCR2KO tumor mice." (PMID 32391790, 2020). "FOXO1, CEBPB, and RELA mRNA expression in stage IV tumor tissues was significantly higher than that in stage II tumor tissues, indicating that the signaling molecule signatures are closely correlated with the tumor stage." (PMID 31395078, 2019). "Mechanistic studies demonstrated that FOXO1-induced miR-200b expression through the GSK3β/β-catenin/TCF4 network-mediated stimulation of ZEB1, which reduced tumor stemness and the epithelial–mesenchymal transition (EMT) signal." (PMID 31754475, 2019). "Nevertheless, the correlation between FOXO1/CEBPB/NF-κB and drug resistance-induced tumor progression is reported in some studies." (PMID 31395078, 2019). "Taken together, our study revealed that miR-96 is a tumor inducer of NSCLC and forms ceRNA regulatory network with FOXO1 and DUSP1 genes to co-regulate NSCLC development depending on EGFR signaling pathway." (PMID 31579447, 2019). "The members of the FOXO subclass (FOXO1, FOXO3, FOXO4 and FOXO6) are involved in a wide range of key biological processes including apoptosis, cell cycle, stress resistance, tumor resistance, differentiation, and metabolism." (PMID 31450545, 2019). "Overexpression of miR-370 in gastric cancer cells promoted the tumor cell proliferation, along with down-regulation of its targets, TGFβ-RII and FOXO1." (PMID 31231497, 2019). "The same trend was observed in human tumor HCT116 cells, where the expression of E1A 12S induced an increase in FoxO1 expression." (PMID 31906031, 2019). "The data showed that FOXO1, CEBPB, and FOXP3 expression in tumor tissues from CRC patients with chemoresistance was dramatically higher than that in chemosensitive tumor tissues." (PMID 31395078, 2019). "Lastly, CRC patients who received neoadjuvant chemotherapy with high levels of FOXO1, CEBPB, and CCL20 in tumor tissues showed worse overall survival." (PMID 31395078, 2019). "In our study, both FOXO1 and DUSP1 presented correlation with miR-96 that is considered as a tumor inducer in researches." (PMID 31579447, 2019). "Protein and total RNA were then extracted from each tumour and used to assess the expression levels of HIF-1α, FoxO1, Sesn3, MnSOD and catalase." (PMID 31905813, 2019). "The other main pathway was pathway in cancer, and the genes in this pathway can impact tumor cell proliferation (PPARG, RAF1), regulate hepatic glucose and lipid metabolism (FOXO1), and decrease the viability and invasiveness of HCC cells (RALA)." (PMID 31799078, 2019).
tumor (continued). "BIRC5, FOXO1 and SQSTM1 protein expression level were detected by immunohistochemistry (IHC) in 302 HCC tissues and in 41 non-tumor tissues." (PMID 29707114, 2018). "The data of IHC analysis demonstrated that positive FOXO1 expression was detected in 190 of 302 HCC tissues (62.91%), whereas 29 of 41 non-tumor tissues (70.73%) showed high FOXO1 expression." (PMID 29707114, 2018). "Together, these data suggest that the PAX3 promoter engages in interactions with potential FOXO1 regulatory elements in the translocated chromosome in ARMS tumours, interactions that are restricted to the wild-type 3' TAD border of the FOXO1 locus." (PMID 28615069, 2017). "The gene profiles indicated that YM155 down-regulated ID1 and BIRC5 which are tumour promoters, and upregulated CYLD and FOXO1 which are tumour suppressors." (PMID 28582447, 2017). "The FOXO family members, FOXO1, FOXO3 and FOXO4, are ubiquitously expressed transcription factors that function as tumor suppressors through inhibiting the expression of genes promoting proliferation, survival or de-differentiation." (PMID 27966458, 2017). "Methylseleninic acid (MSA) treatment increased FOXO1 expression in the presence of EWS-FLI1, induced massive cell death and decreased xenograft tumor growth dependent on FOXO1." (PMID 27740934, 2017). "We found that patients with a tumor showing JNK activation and FOXO1 inactivation had a higher survival rate than those with other combinations (P = 0.004)." (PMID 27268017, 2016). "With sequential morphoproteomic profiling on such a case in conjunction with personalized tumor graft testing, we provide an expanded definition of the biology of PAX3-FKHR (FOXO1) ARMS that integrates genomics, proteomics and pharmacogenomics." (PMID 27323832, 2016). "Several studies demonstrated miR-182 involvement in HCC and metastasis, by controlling the expression of genes with tumor suppressor activity, such as the metastasis suppressor MTSS1, Cebpa, ephrinA5, and FOXO1." (PMID 26728044, 2016). "A xenograft mouse model further revealed that metformin suppressed HEC‐1B tumor growth, accompanied by downregulated ki‐67 and upregulated AMPK phosphorylation and nuclear FOXO1 protein." (PMID 27636742, 2016). "The in vivo study further verified that metformin suppresses tumor growth, accompanied by downregulated ki‐67 and upregulated AMPK phosphorylation and nuclear FOXO1 protein." (PMID 27636742, 2016). "In addition, we also found that the basal expression of EGFR was maintained at a stable level when FoxO1/3a were inhibited, which indicated that EGFR could also be mediated by some other transcription factors when FoxO1/3a lose their functions with the activated AKT pathway in tumor cells." (PMID 25654224, 2015). "The FOXO family of transcription factors (FOXO1, FOXO3A, and FOXO4) function as redundant tumor suppressors in lymphocytes." (PMID 25576920, 2015). "The tumor suppressor genes, PHLPP2 and FOXO1, are the direct targets of miR-135a and transcriptionally downregulated by miR-135a." (PMID 25888950, 2015). "FOXO1, a member of the forkhead box O (FOXO) subfamily of transcription factors, functions as a tumor suppressor and regulates genes involved in the apoptotic response, cell cycle checkpoints and cellular metabolism." (PMID 25888950, 2015). "Taken together, the tumor-induced muscle atrophy is likely due to elevated levels of TNF-α and myostatin, which act together to activate NF-κB and FoxO1 so as to amplify the expressions of calpain (autolysis) and ubiquitin ligases (ubiquitin-proteasome)." (PMID 25797259, 2015). "Skeletal muscle expresses three FoxO family members, including FoxO1, FoxO3 and FoxO4, with both FoxO1 and FoxO3a significantly upregulated in cachectic muscles from LLC and C26 tumor-bearing mice." (PMID 25539728, 2014). "MK-801 dephosphorylated Thr24 in FOXO1 and induced its nuclear translocation, thus increasing transcription of TXNIP, a tumor suppressor gene." (PMID 24112473, 2013).